ALDH3A2 (aldehyde dehydrogenase 3 family member A2)
Description:
Catalyzes the oxidation of medium and long chain aliphatic aldehydes to fatty acids. Active on a variety of saturated and unsaturated aliphatic aldehydes between 6 and 24 carbons in length. Responsible for conversion of the sphingosine 1-phosphate (S1P) degradation product hexadecenal to hexadecenoic acid.
Synonyms: ALDH10; FALDH; SLS
Tractability: Antibody: UniProt predicts a signal peptide or a membrane-spanning region. PROTAC: ubiquitination databases record sites on it; its protein half-life has been measured.
Target class: Enzyme; Oxidoreductase
Gene: Protein-coding gene on chromosome 17 (19,647,291 to 19,685,760, forward strand). Ensembl gene ENSG00000072210.
Subcellular location: Microsome membrane; Endoplasmic reticulum membrane
Subcellular location (Human Protein Atlas): Cytosol; Endoplasmic reticulum
Pathways (Reactome):
Metabolism: Alpha-oxidation of phytanate; Sphingolipid catabolism
Protein localization: Class I peroxisomal membrane protein import; Insertion of tail-anchored proteins into the endoplasmic reticulum membrane
Signal Transduction: RND1 GTPase cycle; RND2 GTPase cycle
Gene Ontology:
Molecular function: aldehyde dehydrogenase (NAD+) activity; farnesal dehydrogenase (NAD+) activity; fatty aldehyde dehydrogenase (NAD+) activity; long-chain fatty aldehyde dehydrogenase (NAD+) activity; long-chain-alcohol oxidase activity; medium-chain fatty aldehyde dehydrogenase (NAD+) activity; protein binding; protein homodimerization activity; 3-chloroallyl aldehyde dehydrogenase activity; oxidoreductase activity; oxidoreductase activity, acting on the aldehyde or oxo group of donors, NAD or NADP as acceptor
Biological process: aldehyde metabolic process; central nervous system development; epidermis development; hexadecanal metabolic process; peripheral nervous system development; phytol metabolic process
Cellular component: intracellular membrane-bounded organelle; cytoplasm; cytosol; endoplasmic reticulum membrane; membrane; peroxisomal membrane; endoplasmic reticulum
Genetic constraint (gnomAD): Loss-of-function variants: 33 observed, 45.39 expected, observed/expected ratio (o/e) 0.73, 90% interval 0.55 to 0.97. The upper end of that interval is the gene's LOEUF score, 0.97, which puts it in group 4 of 6, group 1 being the genes least tolerant of losing a copy. Missense variants: 548 observed, 614.78 expected, observed/expected ratio (o/e) 0.89, 90% interval 0.83 to 0.96. Synonymous variants: 199 observed, 216.43 expected, observed/expected ratio (o/e) 0.92, 90% interval 0.82 to 1.03.
Homologues: Orthologues: chimpanzee ALDH3A2 (98% identical), macaque ALDH3A2 (96% identical), rabbit ALDH3A2 (88% identical), guinea pig ALDH3A2 (85% identical), rat Aldh3a2 (85% identical), mouse Aldh3a2 (84% identical), pig ALDH3A2 (82% identical), tropical clawed frog aldh3a2 (65% identical), zebrafish aldh3a1 (57% identical), Caenorhabditis elegans alh-2 (24% identical), Caenorhabditis elegans alh-1 (24% identical), Caenorhabditis elegans alh-3 (23% identical), and 2 more. Paralogues in human: ALDH3A1 (61% identical), ALDH3B1 (51% identical), ALDH3B2 (40% identical), ALDH1A2 (26% identical), ALDH1A3 (26% identical), ALDH1A1 (25% identical), ALDH2 (25% identical), ALDH1B1 (24% identical), ALDH1L2 (24% identical), ALDH9A1 (23% identical), ALDH1L1 (23% identical), ALDH8A1 (23% identical), and 5 more.
Diseases named in the same sentence as ALDH3A2 in open-access papers:
ALDH3A2 is named in the same sentence as 80 diseases in open-access papers, as found by Europe PMC text mining. Sharing a sentence is not in itself a finding about the gene and the disease. The quoted sentences say what the papers report.
Sjögren-Larsson syndrome (23 papers, 2012 to 2025). "ALDH3A2 loss - of - function or mutation can cause Sjögren - Larsson syndrome, an autosomal recessive disorder with symptoms like ichthyosis, mental retardation, and spastic paralysis." (PMID 40692709, 2025). "ALDH3A2 mutations cause lipid accumulation in skin and brain membranes, leading to Sjögren-Larsson syndrome." (PMID 41292832, 2025). "Sjögren-Larsson syndrome is an autosomal recessive neurocutaneous disorder caused by mutations in the ALDH3A2 gene that affect the fatty aldehyde dehydrogenase synthesis, resulting in overproduction of long-chain aliphatic aldehydes and alcohols." (PMID 38653487, 2024). "Sjögren-Larsson syndrome is caused by mutational inactivation of the fatty aldehyde dehydrogenase ALDH3A2, which is required to transfer SL-derived substrates to the glycerol phospholipid pathway." (PMID 30683667, 2019). "Ultimately, whole-exome sequencing revealed a heterozygous compound mutation in the ALDH3A2 gene that corresponds to Sjogren-Larsson syndrome: an exon 9 deletion (1291-1292delAA) from the mother and an exon 5 splicing mutation (798 + 1delG) from the father." (PMID 30157790, 2018). "Mutations in the ALDH3A2 gene, encoding the human ortholog of yeast Hfd1p fatty aldehyde dehydrogenase, cause Sjögren-Larsson syndrome, a rare neurocutaneous disorder." (PMID 28845213, 2017). "ALDH3A2 is also known as fatty-aldehyde dehydrogenase (FALDH) because of its role in protecting against lipid peroxidation; loss of ALDH3A2 activity is the cause of Sjogren-Larsson syndrome." (PMID 24758227, 2014). "ALDH3A2, a member of the aldehyde dehydrogenase 3 family, is critically important in the detoxification of aldehydes that are generated by alcohol metabolism and lipid peroxidation, and mutations in this gene cause Sjogren-Larsson syndrome." (PMID 35893817, 2022). "Sjogren Larsson syndrome is a genetic disorder characterised by scaling skin, speech abnormalities, intellectual disability and spasticity caused by an autosomal recessive mutation in ALDH3A2, resulting in accumulation of aldehydes." (PMID 34055881, 2021). "ALDH3A2 mutation has been reported to cause Sjögren-Larsson syndrome and the variation of ALDH9A1 maybe a related pathogenic factor of renal cancer." (PMID 34748517, 2021). "The loss of FALDH/ALDH3A2 function causes Sjögren-Larsson Syndrome in humans." (PMID 34237064, 2021). "ALDH3A2, which is in the aldehyde dehydrogenase 3 family, member A2, is critically important in the detoxification of aldehydes generated by alcohol metabolism and lipid peroxidation, and mutations in this gene cause Sjogren-Larsson syndrome." (PMID 33148208, 2020). "Furthermore, phytanic acid alpha oxidation is fully normal in patients suffering from Sjögren Larsson syndrome (SLS) caused by mutations in the ALDH3A2 gene." (PMID 26858947, 2015). "Sjogren-Larsson syndrome (SLS) is a neurocutaneous disease with an autosomal recessive inheritance, caused by mutations in the gene that encodes fatty aldehyde dehydrogenase (ALDH3A2)." (PMID 37793403, 2023). "Defects in the ALDH3A2 gene can lead to Sjögren-Larsson syndrome (SLS), patients who are afflicted with this condition develop spastic diplegia and mental impairment, as well as ichthyosis." (PMID 36474209, 2022). "Phytanic acid is completely broken down in the liver and a fatty aldehyde dehydrogenase, FALDH encoded by ALDH3A2, plays a key role in the process as its defect causes Sjögren-Larsson syndrome." (PMID 22577367, 2012). "Τhe Sjögren-Larsson syndrome (SLS) is a neurological condition that follows an autosomal recessive pattern of inheritance and its genetic basis is a wide variety of mutations in the Aldh3a2 gene, which encodes the fatty aldehyde dehydrogenase (FALDH)." (PMID 37686694, 2023). "No SNVs were detected in the causative gene of Sjögren-Larsson syndrome (ALDH3A2)." (PMID 25417924, 2014).
Sjögren-Larsson syndrome (continued). "Sjögren-Larsson Syndrome (SLS), now termed ALDH3A2-syndromic epidermal differentiation disorder (sEDD), is a rare genetic disorder marked by thickened skin, spasticity, and intellectual disability." (PMID 41046861, 2025).
ichthyosis (10 papers, 2014 to 2025). Disorders of cornification that are characterized by visible scaling and/or hyperkeratosis of most or all of the skin. "Lastly, 3 variants, including the nonsense p.Glu295*, were found in ABHD5, associated with Chanarin–Dorfman syndrome (aka neutral lipid storage disease with ichthyosis); and 5 variants, including the known pathogenic p.Asp221Asn allele, in ALDH3A2, associated with Sjogren–Larsson syndrome." (PMID 38791074, 2024). "This type of ichthyosis is characterized by mutations in the ALDH3A2 gene encoding the microsomal nicotinamide adenine dinucleotide (NAD)-dependent enzyme fatty aldehyde dehydrogenase (FALDH), which is required for the oxidation of long-chain aliphatic aldehydes into fatty acids." (PMID 35269649, 2022).
gastric cancer (7 papers, 2022 to 2025). A primary or metastatic malignant neoplasm involving the stomach. "High expression of ALDH3A2 in the tumor tissue has been shown to be associated with prolonged overall survival in patients with gastric cancer and clear cell renal cell carcinoma." (PMID 35515127, 2022). "For instance, the high expression of ALDH3A2 correlated with low-grade and longer OS in gastric carcinoma patients." (PMID 35053305, 2022). "Moreover, the immunohistochemistry results from HPA database showed that FKBP10 was upregulated in gastric cancer tissues, while ALDH3A2 and MAOA were downregulated in gastric cancer tissues, when compared with corresponding non-cancerous tissues." (PMID 36915111, 2023). "Similarly, the expression of ALDH3A2 was downregulated in gastric cancer tissue compared to normal tissue." (PMID 35515127, 2022). "The high expression of ALDH3A2 could improve the prognosis of gastric cancer by remarkably increasing the M1 macrophages to induce an antitumor immune response and kill tumor cells." (PMID 35893817, 2022). "An another study found that the fatty aldehyde dehydrogenase (FALDH) gene,ALDH3A2 could effectively predict the prognosis of gastric carcinoma (GC) patients and may be an independent prognostic biomarker." (PMID 37081394, 2023).
leukemia (7 papers, 2021 to 2025). A malignant (clonal) hematologic disorder, involving hematopoietic stem cells and characterized by the presence of primitive or atypical myeloid or lymphoid cells in the bone marrow and the blood. "Moreover, ALDH3A2 depletion caused ferroptosis in leukemia cells and acted synergistically with GPX4 inhibition." (PMID 39397802, 2024). "Furthermore, ALDH3A2 depletion caused iron depletion in leukemia cells and preserved normal hematopoietic function." (PMID 39397802, 2024). "While some ALDH family members are known to oxidize 4HNE and other aldehydes to their corresponding acids, only recently have ALDH3A1 and ALDH3A2 been recognized as being associated with ferroptosis resistance in head and neck cancers, gastric tumors, and leukemia cells." (PMID 36274088, 2022). "The inhibition of ALDH3a2 induces ferroptosis and exerts synergistic anti-leukemia effects with GPX4 inhibition or standard chemotherapy with cytarabine plus daunorubicin in vivo." (PMID 37190037, 2023). "At present, the dependence of leukemia cells on aldh3a2 has been observed in a variety of mouse and human myeloid leukemia." (PMID 35559049, 2022). "In addition, studies have shown that leukemia cells rely on aldhyde dehydrogenase 3a2 (aldh3a2) enzyme to oxidize long-chain fatty aldehydes to prevent cell oxidative damage, but do not rely on normal myeloid cell counterparts." (PMID 35559049, 2022). "Therefore, Aldh3a2 inhibition in combination with ferroptosis inducers may represent a promising approach for leukemia therapy." (PMID 39376985, 2024). "The absence of Aldh3a2 leads to ferroptosis-dependent oxidative cell death in leukemia cells, while normal hematopoiesis remains unaffected." (PMID 39376985, 2024). "In addition, ALDH3a2 is selectively essential in leukemia progenitor cells but not in their normal counterparts, possibly owing to increased oxidative stress in leukemia cells." (PMID 37190037, 2023). "In addition, aldehyde dehydrogenase 3 family member A2 (ALDH3A2), an enzyme that oxidizes long-chain aldehydes to prevent oxidative damage, is critical to prevent ferroptosis in leukemia cells but not normal hematopoietic cells." (PMID 33499222, 2021).
ovarian carcinoma (5 papers, 2021 to 2025). A malignant neoplasm originating from the surface ovarian epithelium. "Similarly, in ovarian cancer, ALDH3A2 modulates ovarian cancer cell survival via mediating ferroptosis." (PMID 41444219, 2025). "Afterward, univariate Cox regression analysis was performed to evaluate the prognostic value of each tryptophan metabolism-related gene in the TCGA ovarian cancer cohort, with IDO1, ALDH3A2, HADHA, OGDHL associated with risk values, and CAT, WARS1 involved in protective factors." (PMID 38468343, 2024). "High ALDH3A2 expression predicts poor prognosis in ovarian cancer." (PMID 38844980, 2024).
prostate carcinoma (4 papers, 2016 to 2023). A carcinoma that arises from epithelial cells of the prostate gland. "Additionally, we report a number of novel genes with biological plausibility; this is the first study to report on the association between GPI and ALDH3A2 with prostate cancer in a human population." (PMID 27980733, 2016). "In prostate cancer, the expression of ALDH3A2 was decreased in the primary cancer tissue compared to the healthy prostate tissue but increased in response to anticancer treatments." (PMID 35515127, 2022). "By analyzing six primary prostate cancer specimens and eight prostate cancer cell lines, it was indicated that ALDH isoforms with higher expression levels were ALDH3A2, ALDH4A1, ALDH7A1, ALDH9A1, and ALDH18A1." (PMID 37686694, 2023). "Furthermore, it has been demonstrated that ALDH4A1 and ALDH9A1 are the primary enzyme isoforms responsible for ALDEFLUOR activity in prostate cancer tissues, whereas ALDH3A2 and ALDH18A1 are the predominant enzyme isoforms in non-tumor tissues and high-grade prostate intraepithelial neoplasia." (PMID 37686694, 2023).
acute myeloid leukemia (3 papers, 2021 to 2025). Acute myeloid leukemia (AML) is a group of neoplasms arising from precursor cells committed to the myeloid cell-line differentiation. "Moreover, in acute myeloid leukemia (AML) cells, ALDH3A2 has been demonstrated to regulate ferroptosis and contribute to AML drug resistance by controlling cellular oxidative damage and fatty acid synthesis." (PMID 41444219, 2025). "In a recent study on acute myeloid leukemia (AML), ALDH3A2 protected AML cells from oxidative death." (PMID 35515127, 2022).
ovarian tumors (3 papers, 2012 to 2025). "The available literature supports that ALDH1A3, ALDH3A2, and ALDH7A1 isozymes are expressed more abundantly in ovarian tumors, particularly in mucinous and endometrioid type tumors." (PMID 30965686, 2019). "Immunohistochemical staining showed significant overexpression of ALDH1A3, ALDH3A2, and ALDH7A1 isozymes in ovarian tumors relative to normal ovarian tissues." (PMID 22852552, 2012).
adenocarcinoma of the esophagus (2 papers, 2022 to 2025). "In several studies, ALDH3A2 downregulation has been associated with metastasis of colorectal cancer, as well as with adenocarcinoma of the esophagus." (PMID 36232996, 2022). "In patients diagnosed with esophageal adenocarcinoma, ALDH3A2 expression was significantly reduced, contributing to aldehyde buildup." (PMID 40923024, 2025). "Aldehyde accumulation in esophageal adenocarcinoma negatively correlates with aldehyde dehydrogenase 3 family member A2 (ALDH3A2) expression." (PMID 40923024, 2025). "Moreover, diminished ALDH3A2 expressions correlate with a poorer prognosis in individuals with esophageal adenocarcinoma." (PMID 40923024, 2025).
clear cell renal cell carcinoma (2 papers, 2022 to 2023). "In renal clear cell carcinoma, low level of ALDH3A2 was related with shorter survival." (PMID 36915111, 2023).
glioma (2 papers, 2021 to 2022). A benign or malignant brain and spinal cord tumor that arises from glial cells (astrocytes, oligodendrocytes, ependymal cells). "In the LGG cohort from the TCGA dataset, ALDHs including ALDH2, ALDH6A1, ALDH5A1, ALDH9A1, ALDH1A1 were upregulated in WHO grade II gliomas while the increased expression of ALDH16A1, ALDH3B1, ALDH3A2, ALDH1A2, ALDH3A1 was found in WHO III grade gliomas." (PMID 35116021, 2021).
liver cancer (2 papers, 2020 to 2022). An epithelial or non-epithelial malignant neoplasm that arises from the liver. "The results showed that ALDH1A1, ALDH1L1, ALDH1L2, ALDH3A1, ALDH3A2, ALDH5A1, and ALDH8A1 gene expressions were significantly different between liver cancer and normal tissues." (PMID 34928471, 2022). "Specifically, miR-193b regulates ALDH3A2 and let-7b interacts with ALDH7A1 in obesity, however, in liver cancer, miR-193b regulates ALDH7A1 and let-7b targets HADHA, they regulate different genes (miR-193b /ALDH7A1, let-7b/HADHA) that participate in the same functional process." (PMID 33121472, 2020).
lung carcinoma (2 papers, 2014 to 2019). "Glutathione S-Transferase Omega 1 (GSTO1), Sulfotransferase Family 2B Member 1 (SULT2B1), ADH1A, ADH1B, and ADH1C were downregulated in lung cancer versus normal tissue, while ALDH3A2 and MTHFD2 were upregulated in lung cancer tissue versus normal adjacent tissue." (PMID 31717324, 2019).
Obesity (2 papers, 2020 to 2022). Accumulation of substantial excess body fat. "HFD-fed mice treated with probiotics had significantly lower DEGs of Abcc3 and Aldh3a2 in the liver, suggesting that the probiotic shows protective effects against diet-induced obesity and its related metabolic liver diseases/disorders." (PMID 35743193, 2022). "When looking at the fatty acid metabolism in obesity and uterine cancer, three miRNA-gene interactions (miR100/ALDH9A1, miR-186/ACAA2 and miR- 193b/ALDH3A2) were shared in common." (PMID 33121472, 2020).
asthma (1 paper, 2021). "An ALDH3A2 gene mutation was reported in accumulation of leukotriene B4, which is a key molecule and a pro-inflammatory mediator in asthma." (PMID 34876009, 2021).
breast carcinoma (1 paper, 2022). "Ours is the first study to evaluate the prognostic role of ALDH3A2 in breast cancer." (PMID 35515127, 2022).
central precocious puberty (1 paper, 2021). "Further to explore the role of ALDH3A2 and ALDH9A1 in central precocious puberty will be interesting." (PMID 34748517, 2021).
colitis (1 paper, 2019). Inflammation of the colon. "RT‐PCR and IHC analysis validated that TOE up‐regulated the expression of Adh5, Aldh3a2 and Acox3, but down‐regulated the expression of CCL20, CXCL5, CCR6 and CXCL1 in DSS‐induced colitis." (PMID 31565850, 2019).
endometrial cancer (1 paper, 2024). Primary or metastatic malignant neoplasm involving the endometrium (mucous membrane that lines the endometrial cavity). "The proteomic profiling of endometrial cancer cell lines revealed that ECC-1 and RL95-2 shared the ALDH isoforms ALDH3A1, ALDH3A2, ALDH3B1, ALDH3B2, ALDH7A1, ALDH9A1, and ALDH18A1 in their proteome." (PMID 38893151, 2024).
esophagus cancer (1 paper, 2019). "We also observed that ALDH2 is expressed at high level by almost all seven analyzed cancer types except for skin cancer, whereas the expressions of ALDH3A1 and ALDH3A2 are higher in lung, pancreatic, and esophagus cancer." (PMID 30220009, 2019).
head and neck squamous cell carcinoma (1 paper, 2025). A squamous cell carcinoma that arises from any of the following anatomic sites: lip and oral cavity, nasal cavity, paranasal sinuses, pharynx, larynx, and salivary glands. "This analysis demonstrated that SLC47A1 was the only common gene interacting with ALDH3A2 in head and neck squamous cell carcinoma (HNSC), kidney renal clear cell carcinoma (KIRC), lung squamous cell carcinoma (LUSC), and uterine corpus endometrial carcinoma (UCEC)." (PMID 41444219, 2025).
Hyperinsulinemia (1 paper, 2005). An increased concentration of insulin in the blood. "The increased expression of the aldehyde dehydrogenases such as Aldh3a2 in mice with higher subcutaneous fat-pad mass is consistent with recent studies that correlate hyperinsulinemia with increased hepatic expression of Aldh3a2." (PMID 15998448, 2005).